Y_RNA (Y RNA )
Gene: Miscellaneous RNA gene on chromosome 7 (77,895,880 to 77,895,992, forward strand). Ensembl gene ENSG00000222432.
Homologues: Orthologues: chimpanzee Y_RNA (98% identical). Paralogues in human: RNY1 (76% identical), Y_RNA (76% identical), Y_RNA (75% identical), RNY1P2 (74% identical), Y_RNA (74% identical), Y_RNA (73% identical), Y_RNA (72% identical), RNY1P11 (71% identical), RNY1P7 (71% identical), Y_RNA (71% identical), RNY1P13 (70% identical), Y_RNA (70% identical), and 87 more.